CBX5 (chromobox 5)
Diseases named in the same sentence as CBX5 in open-access papers (continued):
Sharing a sentence is not in itself a finding about the gene and the disease.
lung fibrosis (2 papers, 2019 to 2025). "Recent studies on the associations between CBX5 and diseases have found that CBX5 regulates tumor cell growth and apoptosis in various cancers, periodontal ligament cell apoptosis in periodontitis, and fibroblast activation in lung fibrosis." (PMID 39151099, 2025). "CBX5 is a potential driver of fibroblast activation in pulmonary fibrosis, but its role in PH has not been studied." (PMID 39151099, 2025). "Previous work has shown that the epigenetic complex G9a/CBX5 represses expression of genes that maintain or restore the quiescent state of lung fibroblasts, and inhibition of G9a can reverse IPF fibroblast activation and experimental lung fibrosis." (PMID 31829168, 2019).
medulloblastoma (2 papers, 2020 to 2024). A malignant, invasive embryonal neoplasm arising from the cerebellum.
adenoma (1 paper, 2012). A neoplasm arising from the epithelium. "In Min-induced adenomas of the small intestine, exon 4−5 transcripts of the Cbx5 coding region are elevated compared to normal intestine." (PMID 22670227, 2012).
endometrial tumors (1 paper, 2022). "As for CBX1 and CBX2—we observed positive association with cancer stemness in liver, lung and endometrial tumors, while CBX4, CBX5, CBX6, and CBX8 exhibit rather weak correlation with cancer stemness in a tumor-specific manner." (PMID 36361869, 2022).
experimental autoimmune encephalomyelitis (1 paper, 2024). An autoimmune demyelinating disease of the central nervous system that is produced experimentally in animals by the injection of homogenized brain or spinal cord in Freund's adjuvant. "Inactivation of Cbx5 in the mouse mirrored most of these transcriptional defects and resulted in hypersensitivity to experimental autoimmune encephalomyelitis." (PMID 39029934, 2024).
glioblastoma (1 paper, 2025). The most malignant astrocytic tumor (WHO grade IV). "We found that compared to differentiated glioblastoma cells (DGC), expression of CBX2, CBX3, and CBX5 were upregulated, while CBX1, CBX4, CBX6, CBX7, and CBX8 were downregulated." (PMID 39988672, 2025).
Hypertension (1 paper, 2018). The presence of chronic increased pressure in the systemic arterial system. "On the other hand, CBX5-Abs may discriminate aCI and TIA induced by DM and/or hypertension, and could reflect the abnormal state of cholesterol." (PMID 29464021, 2018).
Infertility (1 paper, 2020). "CBX5, CBX1 and CBX3 null mutant mice revealed different phenotypic outcomes for the three isoforms: CBX5−/− mice presented a normal phenotype, CBX1−/− led to perinatal lethality, and CBX3−/− to infertility." (PMID 32545538, 2020).
lymph node metastasis (1 paper, 2021). "To further clarify the roles of CBX3, CBX5, and CBX7 in disease progression, we use the UALCAN database to analyze CBX expression in different patients with different disease grades and lymph node metastasis status." (PMID 34966411, 2021).
melanoma (1 paper, 2021). A malignant, usually aggressive tumor composed of atypical, neoplastic melanocytes. "Of the other six significant genes identified in the screen (TRIM28, CDYL2, DMAP1, CBX5, PYGO2), TRIM28 is known to increase melanoma tumor propagation potential." (PMID 33527896, 2021).
metastatic cancer (1 paper, 2025). A carcinoma which has spread from the original site of growth to another anatomic site. "The results showed that the expression levels of CLOCK, along with CBX5, CHN1, CNN3, FNDC1, PALLD, and SULF1, were significantly elevated in metastatic cancer tissues compared to primary cancer tissues." (PMID 41350567, 2025).
multiple sclerosis (1 paper, 2024). A progressive autoimmune disorder affecting the central nervous system resulting in demyelination. "High-depth RNA sequencing reveals down-regulation of HP1α/CBX5 in monocytes of multiple sclerosis patients, associated with major transcriptomic changes and reduced activity of the Integrator complex." (PMID 39029934, 2024). "HP1α/CBX5 is an epigenetic regulator with a suspected role in multiple sclerosis (MS)." (PMID 39029934, 2024).
rectal cancer (1 paper, 2020). A primary or metastatic malignant neoplasm that affects the rectum. "High mRNA expression of CBX5/6 was associated with short overall survival (OS) in rectal cancer patients." (PMID 33014884, 2020). "High mRNA expression of CBX5/6 was associated with short OS in rectal cancer patients." (PMID 33014884, 2020). "In our study, high CBX5 mRNA expression was significantly correlated with short OS in patients with rectal cancer." (PMID 33014884, 2020). "High CBX5 (HR = 6.27, p = 0.039) and CBX6 (HR = 4.27, p = 0.0037) mRNA expression was significantly correlated with short OS in rectal cancer patients." (PMID 33014884, 2020).
triple-negative breast carcinoma (1 paper, 2022). An invasive breast carcinoma which is negative for expression of estrogen receptor (ER), progesterone receptor (PR), and human epidermal growth factor receptor 2 (HER2). "CBX5 was also reported to be involved in the SNHG11-miR-2355-5p/CBX5 axis to affect the proliferation and migration of triple-negative breast cancer (TNBC) cells." (PMID 36140750, 2022).
tumor (29 papers, 2007 to 2025). "Low CBX5 levels were associated with advanced cancer stage and tumor grade." (PMID 34395271, 2021). "CBX3 and CBX5 have been found to promote tumor cell proliferation and migration in vitro and regulate the expression of various cytokines that influence the tumor microenvironment." (PMID 40175347, 2025). "Epithelial cells with higher UVRAG expression showed higher expression of tumor migration-associated genes (HN1, HMGB2, PCNA, and CBX5)." (PMID 37173968, 2023). "The level of CBX5 RNA expression within this developmental-neoplastic lineage was investigated by quantitative transcript analysis of normal and tumor tissue." (PMID 22670227, 2012). "CBX5 RNA transcripts harvested from equivalent amounts of tumor and normal intestinal tissue of B6 ApcMin/+ mice heterozygous and homozygous for the insertion were assayed by real time PCR." (PMID 22670227, 2012). "Reduced E2F5 levels increase CBX5 expression, which may inhibit tumor growth by promoting gene silencing through H3K27me3 binding." (PMID 40175347, 2025). "In the papillary subtype, CBX5 transcriptional level was not significantly deregulated in tumor tissues and did not associate with other clinical parameters." (PMID 36292141, 2022). "Our results revealed the anti-tumor effect of CBX5 in ccRCC." (PMID 34395271, 2021). "Finally, rescue experiments validated that LOXL1-AS1 elicited a tumor-facilitating function in RCC via miR-589-5p/CBX5-mediated manner." (PMID 33185692, 2020). "For example, recent findings have shown that CBX5 is overexpressed in human HCC tissues and it can be correlated with tumor growth and metastasis." (PMID 40175347, 2025). "The high expressions of the CBX family (including CBX2, CBX3, CBX5, and CBX6) in tumor tissues were related to the worse OS of DLBCL patients, whereas high expression of CBX1 was correlated with better prognosis of patients." (PMID 37430195, 2023). "The expression of CBX genes differs across solid tumors and for CBX1, CBX2, CBX3, CBX4, CBX5, and CBX8 is predominantly upregulated, while for CBX6 and CBX7 is mostly downregulated in tumor tissues." (PMID 36361869, 2022). "Specifically, we observed significant upregulation of CBX1, CBX3, and CBX5 members, followed by robust downregulation of CBX7 in tumor tissues." (PMID 36361869, 2022). "We observed significant positive correlation between a high CBX1, CBX2, CBX3, CBX5, and CBX8 expression and higher tumor grade in LIHC and UCEC tumors." (PMID 36361869, 2022). "The results showed there was a trend for higher expression of CBX3 and CBX5 with the progression of LUAD, in terms of worse tumor grade, while the expression of CBX7 showed a decreasing trend." (PMID 34966411, 2021). "As the tumor progressed, patients with more advanced tumor grades tended to express higher mRNA expression of CBX3 and CBX4 but lower mRNA expression of CBX1, CBX5, CBX6, and CBX7." (PMID 34395271, 2021). "Moreover, knockdown of CBX5 significantly inhibited capabilities of sphere and colony formation, migration of CD133+-tumor stem-like cells (TSLCs) in vitro and the tumorigenic engraftment, tumor growth rate, and metastatic tendency to lung caused by lung CD133+-TSLCs in vivo." (PMID 30481161, 2018). "We also revealed a significant positive correlation of CBX1 and CBX5 with tumor dedifferentiation status, although not in all tested tumor types." (PMID 36361869, 2022). "We also found patients with high CBX5 tended to have less aggressive tumor subtypes (not TNBC phenotype)." (PMID 33082469, 2020). "In our study, mRNA and protein expressions of CBX5 were found to be significantly higher in HCC tissues, and mRNA expression of CBX5 was significantly related with patients’ individual cancer stages and tumor grades." (PMID 30481161, 2018). "The downstream promoter, P2, shows RNA polymerase 2 binding in human tumor and ES cell lines, supporting the observation that CBX5 function is not completely lost in the R11 homozygous mouse." (PMID 22670227, 2012).
cancer (24 papers, 2016 to 2025). A tumor composed of atypical neoplastic, often pleomorphic cells that invade other tissues. "CBX5, also known as HP1α, was reported to be associated with several cancers, including GC, PRCA, BRCA, and NSCLC." (PMID 33344640, 2020). "The cancer associated biological function of some were known little about, such as CBX2, CBX5, CDT1, TOPBP1 and RUNX2, but whose implication in cancer worth further exploration based on emerging evidences." (PMID 37917664, 2023). "The expression of CBX1, CBX2, CBX5, and CBX8 significantly positively correlates with cancer stemness in LIHC, LUAD, and UCEC tumors, while CBX6—negatively associates with cancer stemness in LUAD and PAAD tumors." (PMID 36361869, 2022). "Overexpression of CBX5 has been observed in many cancers, such as pulmonary carcinoma, BC and PCa13." (PMID 34117289, 2021). "One additional direct transcriptional regulation was found between MYC and CBX5 proteins, but only in “cancer” K562 network." (PMID 29370181, 2018). "We identified no significant correlated expression pattern between hnRNPA1 and CBX5 in the NCI-60 cancer cell panel." (PMID 26791953, 2016). "This showed 2.9-fold up-regulation of CBX5 relative to hnRNPA1 in MCF7 cells versus non-cancer breast epithelial cells (HMEC) and 0.62-fold down-regulation in MDA-MB-231 cells relative to HMEC." (PMID 26791953, 2016). "CBX5 is another widely reported CBX family protein in cancers." (PMID 36140750, 2022). "Therefore, CBX5 deregulation can play dual mechanistic functions for cancer cell proliferation and metastasis suppression, and the underlying cellular mechanisms are not yet comprehensively known." (PMID 36292141, 2022). "Also, CBX5 was dramatically up-regulated in RCC specimens compared with para-carcinoma tissues." (PMID 33185692, 2020). "Investigation of TCGA (The Cancer Genome Atlas) data set revealed that while Cbx1 and Cbx5 are not regulated, Cbx3 is upregulated in GBM compared to control brain samples, although not due to differential methylation." (PMID 27291091, 2016).
infection (7 papers, 2018 to 2023). The state of being infected such as from the introduction of a foreign agent such as serum, vaccine, antigenic substance or organism. "During infection with the ΔhtrA mutant, CBX5 was activated and CLU, KLF5, SP1, TCF7L2 and UBE2I were inhibited." (PMID 37193047, 2022). "Our findings suggested that BmNPV infection increased the accessibility and expression of CBX5 locus." (PMID 32511266, 2020).
CBX5 also shares sentences with these, for which no sentence is quoted: cervical cancer (2 papers); lung adenocarcinoma (2); periodontitis (2); transient ischemic attack (2); acute myeloid leukemia (1); Anosmia (1); bladder cancer (1); cerebral infarction (1); ciliopathies (1); colorectal cancer (1); COVID-19 (1); dedifferentiated liposarcoma (1); esophageal carcinoma (1); fibrosarcoma (1); HCMV infection (1); HIV-1 infection (1); Hutchinson-Gilford progeria syndrome (1); ICF syndrome (1); intestinal tumors (1); intrahepatic cholangiocarcinoma (1); liver cancer (1); lymphoma (1); metastatic disease (1); myopathy (1); Nestor-Guillermo progeria syndrome (1); Nijmegen breakage syndrome (1); non-small cell lung carcinoma (1); ovarian clear cell adenocarcinoma (1); ovarian insufficiency (1); pancreatic adenocarcinoma (1).
A further 9 diseases each share a sentence with CBX5 in 1 paper.